NF2 (NF2, moesin-ezrin-radixin like (MERLIN) tumor suppressor)
Diseases named in the same sentence as NF2 in open-access papers (continued):
Sharing a sentence is not in itself a finding about the gene and the disease.
schwannomatosis (154 papers, 2009 to 2026). The least frequent form of the rare genetic disorder neurofibromatosis. "Background/Objectives: NF2-related schwannomatosis (NF2-SWN) is a genetic tumor predisposition syndrome of the nervous system caused by pathogenic variants in NF2 encoding the merlin tumor suppressor." (PMID 42073536, 2026). "While most cases arise sporadically, occasional associations with neurofibromatosis type 2 (NF2) and schwannomatosis have been reported." (PMID 41236587, 2025). "These syndromes include NF1 and NF2, schwannomatosis, rhabdoid tumor predisposition syndrome, Gorlin, tuberous sclerosis, Von Hippel-Lindau, Li-Fraumeni, Turcot, and mismatch repair (MMR) deficiency syndrome." (PMID 40546517, 2025). "In NF2-related schwannomatosis, one mutation is inherited in an autosomal dominant fashion and the other mutation then occurs, often as a loss of heterozygosity." (PMID 41300330, 2025). "While most cases are sporadic, associations with NF2, schwannomatosis, trauma, positive family history, and syndromes such as Gorlin-Koutlas have been reported." (PMID 41209860, 2025). "It is important to note that not only NF1 but also other related disorders such as Neurofibromatosis type 2 (NF2) and Schwannomatosis contribute to an increased risk of peripheral nerve sheath malignancies." (PMID 41002920, 2025). "Neurofibromatosis type 2 (NF2), also known as NF2-related schwannomatosis, is primarily caused by loss of function and loss-of-function mutations in the NF2 gene." (PMID 39766034, 2024). "In contrast, all tumors with NF2-related schwannomatosis or NF2 mutation detected in the tumor showed additional 22q loss, and thus bi-allelic loss of NF2." (PMID 38265489, 2024). "In our cohort, we observe NF2 mutations or clinical NF2-related schwannomatosis in 45% of all SP-EPN, while 96% of all tumors show loss of 22q." (PMID 38265489, 2024). "Normally, it is a single lesion but can also be associated with NF2 and, in this case, present with multiple lesions, a phenomenon called schwannomatosis." (PMID 39618570, 2024). "Subtype A comprised mostly of tumors with bi-allelic NF2 loss (60/77, 78%) – these cases had either underlying NF2-related schwannomatosis or NF2 mutations detected in the tumor, all harboring chromosomal loss of 22q." (PMID 38265489, 2024). "Genetic testing confirmed the presence of a loss-of-function mutation in the NF2 gene, confirming the diagnosis of NF2-related schwannomatosis." (PMID 37854660, 2023). "SWN is a clinical distinct entity as a result of germline NF2 (22q-related schwannomatosis), or SMARCB1 (SMARCB1-related schwannomatosis), or LZTR1 variant (LZTR1-related schwannomatosis), which are located centromeric to NF2 on chromosome 22." (PMID 37046591, 2023). "Disfiguring cutaneous tumors, focal neurological deficits (e.g., poor gait, facial weakness, hearing loss), and chronic pain are common symptoms of NF1, NF2, and schwannomatosis, respectively." (PMID 38127915, 2023). "Genetic mutations or deletions of NF2 cause NF2-related schwannomatosis, an autosomal dominant disease predisposing to the formation of benign tumors." (PMID 37280085, 2023). "NF1, NF2 and schwannomatosis are rare tumor predisposition syndromes which are characterized by tumors of the central and peripheral nervous system." (PMID 38012771, 2023). "Mutations in the F2–F3 subdomain altered proliferation in three cell lines and matched patterns of disease mutations in NF2 related-schwannomatosis." (PMID 37280085, 2023). "This is in accordance with previous studies that described microlesions as the underlying pathostructural correlate of both NF2- and schwannomatosis-associated PNP, with microlesions showing identical histological and imaging features in both syndromes." (PMID 35453828, 2022).
schwannomatosis (continued). "Among pediatric and young adult patients with newly diagnosed solitary schwannoma, up to 30% will ultimately be diagnosed with an inheritable tumor predisposition syndrome, i.e. NF2 or less commonly, schwannomatosis." (PMID 35986430, 2022). "While somatic NF2 mutations are commonly found in these tumors, the genetic basis of schwannomatosis is more complex, and causative germline mutations have been found in both the SMARC2B and LZRT1 gene." (PMID 33669386, 2021). "In the case of peripheral nerve schwannomas, the identification of further tumors would have to prompt a further diagnostic work-up to exclude an underlying NF2 or Schwannomatosis." (PMID 33804463, 2021). "A landmark FDA-approved therapy has been achieved for NF1-associated PNs, but similar success for NF2 and schwannomatosis is still needed." (PMID 34885143, 2021). "Diagnosis of NF1, NF2 or schwannomatosis was established by fulfilling the necessary diagnostic criteria according to guidelines in 57/73 patients (76%); in the remaining 16 (19.5%), genetic testing confirmed the diagnosis in addition." (PMID 32506255, 2020). "In schwannomas associated with neurofibromatosis type 2 (NF2) or schwannomatosis, the Nf2 gene, which encodes the tumor suppressor protein moesin-ezrin-radixin-like protein (merlin), is mutated." (PMID 31632194, 2019). "NF2 and schwannomatosis are rare genetic disorders that predispose to the formation of spinal and peripheral nerve schwannomas and have considerable clinical overlap." (PMID 30382390, 2018). "NF comprises 3 genetically distinct conditions (NF1, NF2, and Schwannomatosis) unified by the predisposition to nerve sheath tumors that tend to be histologically benign." (PMID 30355560, 2018). "The overlap with NCBRS is supported by the description of a patient with a SMARCB1 mutation who also developed schwannomatosis due to additional somatic loss of both NF2 copies." (PMID 30123105, 2018). "Each NF type has characteristic symptoms: NF1 is typically associated with disfiguring cutaneous tumors; NF2 is associated with hearing loss, facial weakness, and poor gait; and Schwannomatosis is associated with chronic disabling pain." (PMID 30355560, 2018). "Instead, tumour-specific somatic NF2 mutations were identified which are known to be frequent in schwannomatosis." (PMID 27921248, 2017). "Considerable overlap has been noted between schwannomatosis and NF2 (MIM #101000) in terms of the occurrence of the associated types of tumour, but both diseases are regarded as separate clinical entities." (PMID 27921248, 2017). "Patients with neurofibromatosis 1 (NF1), NF2, and schwannomatosis are at risk for multiple nerve sheath tumors and premature mortality." (PMID 22558206, 2012). "Unlike PNFs, PS is not strongly associated with NF1, although some cases may occur with NF2 or schwannomatosis." (PMID 41209860, 2025). "Plexiform schwannomas, although rare, usually manifest along the nerve plexus as multiple schwannomas clusters and may be sporadic or associated with NF2-related schwannomatosis and other forms of schwannomatosis." (PMID 39157066, 2024). "NF2 and schwannomatosis are often associated with multiple schwannomas." (PMID 39157066, 2024). "To identify potential therapeutic vulnerabilities in the two molecular SP-EPN subtypes, we queried clinical trial databases and literature to select compounds that were currently or recently being investigated in clinical trials for ependymomas or NF2-related schwannomatosis-associated tumors." (PMID 38265489, 2024). "Future work to delineate the effect of this region on VS risk may be performed in NF2-related schwannomatosis patients, exploring a potential association between genotype at the 9p21.3 locus and VS presentation age." (PMID 36546557, 2023).
schwannomatosis (continued). "NF2 mutations may be tumor specific, as in unilateral, sporadic VS, or rare germline mutations leading to bilateral VS and NF2-related schwannomatosis, formerly known as neurofibromatosis type 2 (NF2) (U.S. incidence 1:10,000 versus 1:33,000, respectively)." (PMID 37948527, 2023). "In addition, it can improve diagnostic precision to better discriminate NF2-related schwannomatosis from its differential diagnosis." (PMID 37217995, 2023). "The most common schwannomatosis‐associated gene is NF2, but SMARCB1 and LZTR1 are also associated." (PMID 35723634, 2022). "The specific combination of somatic NF2 mutations may be a major factor in regulating the severity and scope of the resulting phenotype in schwannomatosis." (PMID 36363549, 2022). "There is also a possibility that at least a proportion of the schwannomatosis cases that remain genetically unexplained might be caused by a variant within NF2, SMARCB1, or LZTR1 that has been missed by routine diagnostic methods." (PMID 35723634, 2022). "In addition, the majority of non‐NF2‐related schwannomatosis cases are sporadic, suggesting the existence of novel schwannomatosis variants and/or genes." (PMID 35723634, 2022). "Indeed, some NF2 patients with somatic mosaicism for an NF2 gene mutation fulfil the diagnostic criteria for schwannomatosis." (PMID 27921248, 2017). "The main focus of this review is schwannomatosis, but the considerable clinical overlap between NF2 and schwannomatosis, as well as the shared mutational mechanisms (such as LOH of 22q), render it likely that a similar set of genes is involved in both conditions." (PMID 27921248, 2017). "However, whilst routine genetic analysis is able to identify around 92%−95% of variants responsible for familial cases for NF1 and NF2‐related schwannomatosis, the proportion of familial non‐NF2‐related schwannomatosis cases that can be attributed to known variants is much lower (70%−80%)." (PMID 35723634, 2022). "In comparing NF1, NF2, and schwannomatosis with regard to the respective diagnostic features and symptoms, it is reasonable to hypothesize that C-fiber loss is indeed the cause for pain experienced by schwannomatosis patients." (PMID 32443592, 2020). "Even if it is assumed that a certain proportion of unexplained schwannomatosis cases are caused by somatic mosaicism for an NF2 gene mutation, a subset of these unexplained cases may well be caused by mutations in a gene or genes that still remain to be identified." (PMID 27921248, 2017). "This case highlights schwannomatosis presenting with cauda equina syndrome, emphasizing the importance of early recognition, spinal decompression, and differentiation from NF2 for optimal management." (PMID 40337438, 2025). "Recent advancements in our molecular understanding of these disorders have led to a redefined conceptual framework within the field, grouping NF2-related schwannomatosis with other forms of schwannomatosis." (PMID 40510571, 2025). "Patients with NF2-related schwannomatosis harbored an even distribution of tumor samples with either two distinct nucleotide variants or one variant as the presumed first hit and the LOH of chromosome 22 as the second hit." (PMID 39941762, 2025). "In NF1, NF2, and schwannomatosis (SWN), emerging technical advances, particularly WB-MRI as well as DWI/ADC mapping, in conjunction with clinical and genetic data, can potentially provide insight into both disease severity as well as tumor behavior." (PMID 39030374, 2025). "Until the identification of the schwannomatosis-causing genes LZTR1 and SMARCB1, schwannomatosis was mainly identified by clinical criteria and by the exclusion of germline NF2 PVs." (PMID 40794298, 2025). "The three major schwannomatosis genes, NF2, LZTR1 and SMARCB1, are all located within approximately 9 megabases on chromosome 22 and cause three genetically distinct conditions with significant clinical phenotypic overlap." (PMID 41284083, 2025).
schwannomatosis (continued). "Somatic pathogenic NF2 variants are normally found in tumour DNA from non-NF2-SWN, which historically caused confusion in delineating other forms of schwannomatosis." (PMID 41284083, 2025). "The most common form of schwannomatosis is NF2-related SWN, which is caused by heterozygous pathogenic NF2 gene variants." (PMID 40794298, 2025). "Neurofibromatosis type 1 (NF1, n = 4), type 2 (NF2, n = 1), schwannomatosis (n = 2) and legius syndrome (n = 1) were detected in 13% of the rare disease cohort." (PMID 39061237, 2024). "Understanding TME composition holds promise for systemic therapeutic interventions, particularly for NF2-related schwannomatosis." (PMID 38817895, 2024). "The majority of NF2-related schwannomatosis patients treated with bevacizumab had an overall positive therapeutic response." (PMID 38672561, 2024). "The previously defined "NF2 syndrome" has now been renamed "NF2-related schwannomatosis" (NF2-SWN) and this is the term which will be used in the rest of this article." (PMID 38695575, 2024). "Five patients with NF2-related schwannomatosis underwent multiple surgeries due to the presence of tumour in the cerebellopontine angle." (PMID 38992191, 2024). "One hundred and eighty-six cases of NF2-related schwannomatosis with age at VS presentation data were grouped by genotype (AA = 46 cases, AC = 89 cases, CC = 51 cases)." (PMID 36546557, 2023). "In the recent update (2022 consensus), the role of genetic testing was highlighted to discriminate NF2 from schwannomatosis." (PMID 37217995, 2023). "A significantly increased number of myeloid-derived suppressor cells have been reported in the blood of VS patients with NF2-related schwannomatosis." (PMID 37948527, 2023). "A total of 166 participants (73%) had NF1, 32 (14%) had NF2, and 30 (13%) had schwannomatosis; 217 attended 6 or more of 8 sessions and provided posttest data." (PMID 37378983, 2023). "NF1 is the most common, with an incidence of 1 in 3,000 births, followed by NF2 (1 in 33,000), and schwannomatosis (1 in 60,000)." (PMID 38127915, 2023). "Due to repetitive sequences surrounding lead SNP, rs1556516, no appropriate primer designs were available for direct characterization of rs1556516 in a new cohort of NF2-related schwannomatosis patients." (PMID 36546557, 2023). "This study identifies the PI3K and PAK pathways as potential targets for combination drug treatment of NF2-related schwannomatosis." (PMID 37886501, 2023). "Patients with neurocutaneous syndromes represented 29.6% of our cohort (42/142): 21 patients (14.8%) were affected by NF1, 15 patients (10.6%) by schwannomatosis, and 6 (4.2%) by NF2." (PMID 36698394, 2022). "While chronic pain, the leading symptom of schwannomatosis, is uncommon in NF2 patients, NF2-PNP is characterized by moderate-to-severe sensory deficits and paresis." (PMID 35453828, 2022). "Two of 13 patients (15%) had multiple schwannomas without clinical features of NF1 and were suspected clinically to have NF2 or schwannomatosis." (PMID 35698239, 2022). "There are three major genetic syndromes associated with PNST tumours—Neurofibromatosis 1 (NF1), Neurofibromatosis 2 (NF2) and Schwannomatosis." (PMID 35698239, 2022). "This study included 351 adult participants with NF1 and 43 adult participants with either NF2 or Schwannomatosis (comparison group)." (PMID 35248131, 2022). "In contrast to the accumulation of nerve lesions, primarily in the distal nerve segments in NF2, the lesion numbers in schwannomatosis peak at the mid-thigh level." (PMID 35453828, 2022). "The gene, which is centromeric to NF2 and SMARCB1 on chromosome 22q11.21, was recently uncovered as a germline predisposition gene in schwannomatosis." (PMID 36008825, 2022). "There are 3 clinically and genetically distinct forms of neurofibromatoses (NFs): neurofibromatosis types 1 (NF1) and 2 (NF2) and schwannomatosis." (PMID 35291225, 2022).
schwannomatosis (continued). "Nevertheless, in the mid-1990s a consensus began to develop that the entity schwannomatosis was distinct from NF2, although concern still existed over significant overlap with NF2." (PMID 35361920, 2022). "Despite the considerable pathomorphological overlap, clinical features differ greatly between NF2 and schwannomatosis." (PMID 35453828, 2022). "Our protocol describes the plans to develop the first-ever stand-alone web-based program to address the psychosocial needs of adults with NF1, NF2, and schwannomatosis." (PMID 34110294, 2021). "There are three types of NF: NF1 accounting for 96% of all cases, NF2 in 3%, and schwannomatosis (SWN) in <1%." (PMID 34072574, 2021). "Although there is a phenotypic overlap with NF2, two distinct genes have been identified for schwannomatosis, SMARCB1 and LZTR1." (PMID 34885143, 2021). "Since these tumors also occur in patients with NF2 and Schwannomatosis, any occurrence of more than one peripheral nerve schwannoma mandates a work-up for those diseases." (PMID 33804463, 2021). "It is, however, closely related to schwannomatosis, due to variants in either INI1 (SMARCB1) or LZTR1, which are closely located to NF2 on chromosome 22." (PMID 33445724, 2021). "It should be emphasized that although NF1-, NF2-, and schwannomatosis-related tumors have distinct genetic origins, they share downstream activation of several molecular targets." (PMID 34604034, 2021). "Patients with neurofibromatosis (NF; NF1, NF2, or schwannomatosis) have lower but modifiable quality of life (QoL), higher depression, anxiety, pain, stress, and social isolation compared with the general population." (PMID 34110294, 2021). "The incidence rates of NF1, NF2, and schwannomatosis are 1:3,000, 1:60,000, and 1:70,000 in the general population, respectively." (PMID 33767727, 2021). "Although multiple schwannomas are observed in both NF2 and schwannomatosis, the clinical features of the two syndromes are distinct." (PMID 31161239, 2020). "The existence of a peripheral nerve tumour together with the other diagnostic criteria of schwannomatosis, NF1 or NF2 can pave the road to final diagnosis." (PMID 32506255, 2020). "The decisive diagnostic feature, which separates schwannomatosis clearly from NF1 and NF2, is the marked reduction of IENFD." (PMID 32443592, 2020). "In contrast to neurofibromatosis type 1 (NF1) and NF2, schwannomatosis is characterized by genetic heterogeneity." (PMID 32443592, 2020). "One of the main challenges in diagnosing SS is to differentiate it phenotypically from mosaic NF2 or early NF2 since the latter two can fulfill the current criteria of schwannomatosis." (PMID 31438995, 2019). "Our primary aim was to assess the ability of a non-profit foundation-sponsored clinic network to facilitate access to specialized care for patients with neurofibromatoses (NF), a group of neurogenetic disorders including NF1, NF2, and schwannomatosis (SWN)." (PMID 30157837, 2018). "The size of the cohorts in this study provide useful clinical and genetic insights into both schwannomatosis and NF2 as well as an important caution about the clinical overlap between these conditions." (PMID 30382390, 2018). "Within the strict regional boundaries of a highly ascertained nested study there were 95 NF2 and 44 schwannomatosis cases." (PMID 30382390, 2018). "Most patients seen across the network in 2015 had NF1 (n = 9418, 91.9%) and a minority had NF2 (n = 645, 6.3%) or schwannomatosis (n = 182, 1.8%)." (PMID 30157837, 2018). "Despite considerable phenotypic overlap with NF2, schwannomatosis has been shown to a distinct entity with pathological variants in SMARCB1 and LZTR1 genes." (PMID 30382390, 2018). "A national (UK) NF2 and schwannomatosis database was interrogated to identify patients meeting existing diagnostic criteria." (PMID 30382390, 2018).